MED13 (mediator complex subunit 13)
Diseases named in the same sentence as MED13 in open-access papers (continued):
Sharing a sentence is not in itself a finding about the gene and the disease.
lymphoma (1 paper, 2016). A malignant (clonal) proliferation of B- lymphocytes or T- lymphocytes which involves the lymph nodes, bone marrow and/or extranodal sites. "Lymphoma was found as the only tumor entity to solely show underexpression of its Mediator subunits (most strongly MED28, MED14, MED13, CDK19, all with a frequency of 100%, n = 11/11)." (PMID 27050271, 2016).
microcephaly (1 paper, 2024). A congenital or acquired developmental disorder in which the circumference of the head is smaller than normal for the person's age and sex. "Other features that were reported in patients with MED13 variants included optic nerve abnormalities, hearing loss, growth delay/restriction, hypotonia, mild congenital heart anomalies, epilepsy, and microcephaly." (PMID 38745205, 2024).
Multiple Organ Failure (1 paper, 2024). A progressive condition usually characterized by combined failure of several organs such as the lungs, liver, kidney, along with some clotting mechanisms, usually postinjury or postoperative. "Therefore, we propose to expand the MED13-associated phenotype to include severe complications that could end up with multiple organ failure and neonatal death." (PMID 38745205, 2024).
scoliosis (1 paper, 2012). A congenital or acquired spinal deformity characterized by lateral curvature of the spine. "Fold change analysis of the results permitted to identify Tob2 and MED13 as VDR responsive genes differentially expressed in Juvenile and Adolescent Scoliosis group in muscular tissue samples of curve concavity." (PMID 23259508, 2012).
speech disorder (1 paper, 2018). A term referring to disorders characterized by the disruption of normal speech. "This MED13-associated syndrome is characterized by DD/ID with speech delay and/or speech disorders." (PMID 29740699, 2018).
steatosis (1 paper, 2025). Increased lipid within the cytoplasm of cells. "Overexpression of cardiac MED13 had been shown to prevent weight gain, whereas the loss of skeletal muscle MED13 led to enhanced glucose uptake and glycogen deposition, protecting the liver from steatosis." (PMID 41019282, 2025).
neurodevelopmental disorder (5 papers, 2018 to 2025). A behavioral and cognitive disorder with onset during the developmental period that involves impaired or aberrant development of intellectual, motor, or social functions. "Pathogenic MED13 variants can cause the rare neurodevelopmental disorder IDD, autosomal dominant 61 (MRD61; OMIM 618009), also referred to as MED13-related syndrome." (PMID 41561257, 2025). "It is of particular relevance to this study that variation in the MED13-paralog MED13L has been shown to cause a neurodevelopmental disorder as well." (PMID 29740699, 2018). "We believe that the data presented in this study coupled to the additional evidence available from other studies strongly support the conclusion that rare protein-altering variation in MED13 underlie a new neurodevelopmental disorder." (PMID 29740699, 2018). "In this study, we show that variants in MED13 are also associated with a neurodevelopmental disorder, and delineate the corresponding phenotypic features and mutational spectrum." (PMID 29740699, 2018). "By molecular and clinical characterization of a cohort of 13 patients with variants in MED13, we here provide evidence for a new neurodevelopmental disorder." (PMID 29740699, 2018). "This case is also consistent with haploinsufficiency as the disease mechanism for truncating MED13 variants in MRD61, underscoring the importance of exome sequencing in patients with neurodevelopmental disorders and congenital anomalies." (PMID 41561257, 2025). "It should be noted that several of these regulation motifs are linked to similar neurodevelopmental disorders including MAPK dysfunction and DEG_SCF_FBW7_1, which was observed as modified in multiple individuals with MED13-related neurodevelopmental disorder." (PMID 37106788, 2023). "Also, we have identified 15 de novo variants in genes that were previously implicated in ASD or related neurodevelopmental disorders (PHF21A, WASF1, TCF20, DEAF1, MED13, CREBBP, KDM6B,SMURF1, ADNP, CACNA1G, MYT1L, KIF13B, GRIA2, CHM, and KCNK9)." (PMID 38572415, 2024).
tumor (4 papers, 2014 to 2025). "It comes as no surprise then that studies in Drosophila, Zebrafish, Arabidopsis, and mice have revealed that Med13 plays critical roles in embryonic and tumor development." (PMID 34683473, 2021). "FBW7 exerts its anti-tumor activity by targeting a ever-growing list of ubiquitin substrates including MED13, KLF2, and Mcl-1." (PMID 24899581, 2014). "Emerging evidence exhibits that CDC4 has been confirmed as a tumour suppressor due to the wide involvements in degradation of diverse proteins associated with oncogenic developments, including cyclin E, c-Myc, c-Myb, c-Jun, Notch, MCL1, MED13/13L, PGC-1α, C/EBPα, TGIF1 and KLF5." (PMID 40260685, 2025).
cardiovascular diseases (2 papers, 2016 to 2021). "Therefore, MED13 constitutes a potential therapeutic target for the regulation of metabolic disorders and other cardiovascular diseases." (PMID 33390853, 2021). "Additional research is required to determine whether cardiac MED13 is involved in other cardiovascular diseases and if it regulates cardiac function." (PMID 33390853, 2021).
cancer (1 paper, 2021). A tumor composed of atypical neoplastic, often pleomorphic cells that invade other tissues. "Taken together, our results suggest that loss of MED13 alters expression of multiple genes belonging to cancer-related pathways, and that products of these genes integrated in functional network centered around cyclin D1." (PMID 33444446, 2021). "This MED13 property has a potential to serve as basis for the design of innovative strategies for cancer therapies." (PMID 33444446, 2021). "In conclusion, these findings indicate that MED13 stabilization, through CDK8/19 inhibition with Senexin A, significantly sensitizes cancer cells to treatment with alkylating agents." (PMID 33444446, 2021). "We further demonstrate the therapeutic potential of MED13-mediated response, by applying combinatory treatment with CDK8/19 inhibitor Senexin A. Importantly, the treatment with Senexin A stabilizes MED13, and in combination with alkylating agents significantly reduces viability of cancer cells." (PMID 33444446, 2021).
Cardiac Diseases (1 paper, 2021). "MED13 maintains the transcription of some essential proteins involved in growth and development, and MED13 gene mutations are associated with various diseases, including cardiac diseases." (PMID 33390853, 2021).
neurological disorders (1 paper, 2025). "WES revealed a de novo missense mutation in MED13 (c.C979T; p.Pro327Ser), a variant previously implicated in a newly identified neurological disorder." (PMID 41465117, 2025).
MED13 also shares sentences with these, for which no sentence is quoted: cardiomyopathy (2 papers); Insulin resistance (2); adenocarcinoma (1); Arrhythmia (1); congenital heart disease (1); congenital megacolon (1); Encephalopathy (1); fibrosis (1); heart failure (1); heart malformations (1); hyperthyroidism (1); infantile spasms (1); metabolic disorders (1); Motor delay (1); Retinal dystrophy (1); Right ventricular hypertrophy (1).